NLRP3 (NLR family pyrin domain containing 3)
Diseases named in the same sentence as NLRP3 in open-access papers (continued):
Sharing a sentence is not in itself a finding about the gene and the disease.
infection (continued). "At 24 hours post-infection (hpi), western blot analysis revealed marked upregulation of NLRP3 together with increased expression of pro-IL-1β in CEK cells, which was accompanied by enhanced secretion of mature IL-1β into the culture supernatant." (PMID 41334910, 2025). "Nlrp3 knockdown led to a marked decrease in TUNEL-positive cells in the head at the site of the infection at 4 hpi following localized infection, indicating that Nlrp3 is required for infection-induced cell death." (PMID 41360763, 2025). "As a key regulator of inflammatory response, ARIH2 is important in defense against infection and had been demonstrated to regulate NLRP3 activity in microphages by ubiquitination." (PMID 40953119, 2025). "We also evaluated NRF2 expression in cells infected with dengue virus to analyze its role in the antioxidant response during infection, in addition to reports that demonstrate its involvement in the activation of autophagy and NLRP3 inflammasome." (PMID 41471247, 2025). "MSCs also reduce NOD2 expression, NLRP3 inflammasome activation, and IL-1β secretion in HL-1 cells after infection." (PMID 40433382, 2025). "When specifically examining this macrophage cluster, compared with infected WT mice, NLRP3 KO mouse liver macrophages exhibited marked differences in metabolic pathways post-infection, particularly a downregulation of key enzymes in the glycolytic pathway." (PMID 41190868, 2025). "The innate immune response to cell infection relies on receptors including Nod-like receptors (NLRs); particularly, NLRP3 is one of the best-characterized receptors that is involved in multiple inflammatory diseases." (PMID 39934686, 2025). "Under metabolic stress, infection, or organelle dysfunction, NLRP3 translocates to endolysosomal vesicles enriched in LAMP1 and phosphatidylinositol-4-phosphate (PI4P), facilitating its spatial anchoring and oligomerization." (PMID 40959087, 2025). "Following a 4-hour exposure to infection, NLRP3 knockout cells displayed a significantly greater fraction of labeled TCA cycle metabolites, including citrate, relative to parental cells." (PMID 41190868, 2025). "Upon exposure to infection or various stressors, the activity of FoxO3a can be modulated, influencing the activation of NLRP3 inflammasomes, resulting in the intracellular release of inflammatory mediators that subsequently initiate pyroptosis." (PMID 41371168, 2025). "We also found considerable heterogeneity at the single-cell level, as DCs activated either caspase-11 and NLRP3 inflammasome-dependent pyroptosis early during infection or apoptosis later during infection." (PMID 40530878, 2025). "In support of these in cellulo findings, in vivo studies utilizing both NLRP3 knockout mice and infection with either wild-type or RVFV-NSsRM virus further demonstrated that NSs promotes inflammation through NLRP3 inflammasome activation." (PMID 41157666, 2025). "Among genes associated with pathogen recognition, CARD14 was most prominently up-regulated during clade I and IV infection at 48 HPI, while NLRP3 (a key inflammasome component) was expressed during clade III infection at 24 HPI." (PMID 41419766, 2025). "To investigate how L. infantum dampens NLRP3-related inflammatory responses in microglia, we examined the effect of infection on NF-κB p65 (RelA), a central transcription factor crucial for the priming phase of NLRP3 activation." (PMID 41162989, 2025). "While lung expression of TLR3, DDX58 and NLRP3 remained unchanged in WT mice following infection, it was significantly higher in TLR7 KO mice." (PMID 40442368, 2025). "infection dampens NLRP3 activation by modulating mitochondrial ROS production, partly through upregulation of antioxidant enzymes such as superoxide dismutases (SOD1 and SOD2), catalase (CAT), and glutathione peroxidase (GPx)." (PMID 41404367, 2025). "It is possible that Lug14 coordinates with other Dot/Icm effectors to modulate the activity of NLRP3 at different stages of infection." (PMID 40953119, 2025).
infection (continued). "This review examines the role of the P2X7/NLRP3/IL-1β pathway in mediating the effects of infection and neuronal inflammation on brain development." (PMID 40713568, 2025). "Macrophages, key immune cells in infection defense, play a vital role in pathogen clearance through polarization (M1/M2) and NLRP3 inflammasome activation." (PMID 40572155, 2025). "During the course of infection, miRNA-223 is involved in restricting the activation of the NLRP3 inflammasome and cytokine-driven inflammation." (PMID 39901167, 2025). "These processes not only compromise cellular bioenergetics but also influence immune signaling cascades, such as cGAS-STING and NLRP3 inflammasome pathways, thereby shaping infection outcomes." (PMID 41404367, 2025). "From the development of the infection model with M. smegmatis, we observed that CP and DE reduced NLRP3 inflammasome levels during infection." (PMID 40142455, 2025). "Murine studies have demonstrated that neonatal activation of the NLRP3 inflammasome, triggered by inflammatory stimuli such as infection, can result in persistent neurodevelopmental alterations." (PMID 41149694, 2025). "Infections, such as severe fever with thrombocytopenia syndrome virus, trigger mitochondrial dysfunction and ox-mtDNA release, activating the NLRP3 inflammasome." (PMID 40307577, 2025). "Compared to mock controls, H6N6 infection significantly upregulated NLRP3, caspase-1, and GSDMD mRNA at 12, and 24 hpi (p < 0.05)." (PMID 41305513, 2025). "Miscarriage, a distressing pregnancy complication often triggered by infection, induces NLRP3 expression and activation, making the inflammasome a potential therapeutic target." (PMID 41231359, 2025). "To identify the inflammasome sensors responsible for the recognition of A. baumannii, we inoculated WT BMDMs with A. baumannii 1605 and measured Nlrc4, Aim2, Nlrp3 and Caspase-11 transcript levels in cell lysates at 6- and 12-hours post infection." (PMID 39533032, 2024). "The involvement of Mtb in the NLRP3-dependent inflammasome during infection is characterized by recent studies." (PMID 38785795, 2024). "DENV can facilitate the assembly of NLRP3 inflammasome during infection, which then regulates the cleavage of inactive pro-IL-1β (interleukin 1 beta, IL1B) via activating Caspase-1 (CASP1), a process that yields mature IL1B, thereby activating inflammation." (PMID 38355571, 2024). "So, the intracellular infection of S. pseudintermedius facilitated the activation of the NLRP3-GSDMD signalling pathway and induced pyroptosis, which was relieved with the decrease of ROS." (PMID 38515339, 2024). "IHC staining of lung tissues from Nlrp3–/– mice revealed an increased recruitment of Ym1hi myeloid cells after PA infection." (PMID 39405117, 2024). "Potential stimuli for NLRP3 activation during infections are helminth products that are either soluble or exosomal, and endogenous signals from inflammation and injured tissue." (PMID 38623843, 2024). "Nucleotide-binding oligomerization domain (NOD)-like receptor family pyrin domain containing 3 (NLRP3) Inflammasome, serving as a sensor of infections and external stimuli, are involved in the pathological processes of various diseases." (PMID 39026932, 2024). "The presence of V. vulnificus in the bloodstream led to infections in WT, Gsdmd−/−, and Nlrp3−/− mice in the EE‐YJ group." (PMID 39605303, 2024). "The research discussed here indicates that T. gondii products are able to activate the NLRP3 inflammasome, which then produces IL-1β to control the infection." (PMID 38623843, 2024). "Using a RVFV infected mouse model and a mutant virus that did not trigger transcription inhibition, we showed that RVFV-triggered NLRP3 activation contributed to viral pathogenesis and fatal infection in vivo." (PMID 39213434, 2024). "Upon cellular stimulation by various triggers such as injury, infection, or oxidative stress, the NLRP3 protein undergoes conformational alterations." (PMID 38399989, 2024).
infection (continued). "NLRP3 belongs to the nucleotide-binding oligomerization domain (NOD)-like receptor (NLR) family of intracellular pattern-recognition receptors that sense infections or cellular perturbations." (PMID 39188718, 2024). "A massive increase in peritoneal eosinophils was evident as early as 4 weeks of infection, where despite of similar percent of eosinophils (shown in plots), absolute numbers were higher in NLRP3−/− mice than those numbers found in Taenia-infected WT mice." (PMID 38842647, 2024). "The NLRP3 inflammasome works as a sensor of potential infection and toxicity and is important in the pathogenesis of different conditions." (PMID 39026932, 2024). "Immunofluorescence staining was conducted on day 3 post-infection to examine the expression of NLRP3 and ASC in lung tissue." (PMID 38675960, 2024). "Infection of BMDMs with Leishmania has been reported to trigger NLRP3 inflammasome activation, leading to the release of mature IL-1b." (PMID 39696675, 2024). "There are multiple potential mechanisms of SARS-CoV-2's impact on bone metabolism, including direct infection of bone marrow cells, inflammation, and activation of the NLRP3 inflammasome." (PMID 38236510, 2024). "All these cell types are exposed to infection by pathogens, but the different expression profiles of NLRP3, NLRP6, NLRP10, and NLRP12 probably reflects that each cell type has a distinct cell physiology that pathogens would evolve to target." (PMID 39076995, 2024). "Further, infection with Chlamydia trachomatis has been shown to increase NLRP3-dependent caspase-1 activation in cervical endothelial cells." (PMID 39769450, 2024). "•The study highlighted that CV-A16 and CV-A10 infections triggered cell death probably involved in NLRP3-mediated pyroptosis and inflammatory response." (PMID 38705479, 2024). "Activation of the NLRP3 inflammasome in these cells contributes to the clearance of M. tb and the resolution of infection." (PMID 39125766, 2024). "The NLRP3 inflammasome is critical for host immune defences against several types of infections, including bacterial, fungal, and viral." (PMID 38623843, 2024). "Compared to uninfected controls, infection with SARS-CoV-2 resulted in an enriched NLRP3 pathway (Normalized Enrichment Score, NES 1.41, P-value = 0.043)." (PMID 38748756, 2024). "The NLRP3 inflammasome activation has been reported to have a protective or detrimental role during infection with different Leishmania spp., depending on the spp." (PMID 39250503, 2024). "The NLRP3 inflammasome plays an important role in protecting the host from infection and aseptic inflammation, and its regulatory mechanism is not completely understood." (PMID 38267403, 2024). "Nod-like receptor protein 3 (NLRP3) is a crucial player in regulating host immune responses to infection and cells stress, and it was also found highly expressed in pSS patients than control." (PMID 38376769, 2024). "For example, EV-A71 infection activates the NLRP3 inflammasome in macrophages and promotes the production of IL-1β to increase vascular permeability." (PMID 39767680, 2024). "It is clear that NLRP3 activation is one of the vital innate events during E. histolytica, resulting in an inflammatory response that will control the infection’s progression." (PMID 38623843, 2024). "Of note, infection of mice with murine beta coronavirus A59 increases NLRP3 inflammasome-mediated inflammation." (PMID 37934800, 2024). "Compared to untreated control and S. mitis-infected macrophages, S. anginosus infected macrophages significantly increased NLRP3 protein expression at 6 h post-infection." (PMID 38289109, 2024). "RVFV infection of Nlrp3-/- mice resulted in a significantly lower mortality rate than infection of WT mice." (PMID 39213434, 2024). "A previous study reported that infection of murine dendritic cells with attenuated strains rMP-12 or RVFV deleted of NSs can trigger IL-1β release into the supernatant in the NLRP3-dependent manner only with LPS priming." (PMID 39213434, 2024).
infection (continued). "ZIKV, an RNA virus, has been reported to promote NLRP3 inflammasome activation to benefit its infection by stabilizing caspase-1 to suppress cGAS-mediated type I IFN signalling." (PMID 38426093, 2024). "This receptor controls the expression of inflammatory markers, such as NLRP3 and IL-1β, which helped control parasitic replication during infection with the EGS strain." (PMID 39267751, 2024). "As an ISG, ZNFX1 is rapidly upregulated together with NLRP3 during the early stages of infection, keeping NLRP3 in check." (PMID 39333773, 2024). "Our findings revealed a significant upregulation of pro-inflammatory cytokines and the NLRP3 inflammasome in RAW 264.7 cells following a 4-hour infection with K. quasivariicola." (PMID 38585654, 2024). "Genetic deficiency or therapeutic inhibition of NLRP3 in mice has been shown to result in greater resistance to H3N2 and H7N9 infections." (PMID 39459869, 2024). "SAECs expressed the NLRP3 protein and at one day post-infection the level of cleaved IL-1α was increased." (PMID 38664396, 2024). "What mechanisms were involved in the CCECs intracellular infection of S. pseudintermedius, and what are the relationships among intracellular infection, NLRP3 inflammasome, and pyroptosis?" (PMID 38515339, 2024). "Upon 8 weeks of infection an abundant population of eosinophils was observed within peritoneal cavity of WT mice, where parasites were still present, in contrast, in NLRP3−/− mice a significantly reduced population of eosinophils was found." (PMID 38842647, 2024). "A key limitation was the exclusion of pro-inflammatory cytokines, such as IL-1β and NLRP3, which are gold standards for distinguishing between general inflammation and infection." (PMID 39590856, 2024). "In P. leopardus, TLR5, NOD2, and NLRP3 were all notably induced in the spleen and liver from 6 to 12 h or 24 h post-infection, and the predicted protein structures of three genes were similarly to those of mammals or other fishes." (PMID 39450165, 2024). "In the infection group, the relative mRNA expression of NLRP3 and GSDMD was significantly raised compared to the control group (p < 0.01)." (PMID 38515339, 2024). "It is obvious that NLRP3 inflammasome activation is influenced by the strain of T. cruzi during the infection course." (PMID 38623843, 2024). "NOD-like receptor protein-3 (NLRP3) as one of these members, is recruited against tissue damage, infection, and metabolic stress." (PMID 38390570, 2024). "The addition of MCC950 also decreased the ROS and MDA accumulation in cells during infection, perhaps by inhibiting the NLRP3 inflammasome activation and reducing inflammatory damage to the cells, consistent with the findings of Bowei Ni." (PMID 38515339, 2024). "Infection of Gsdmd-/- mice with L. amazonensis was recently reported to induce lesion exacerbation, a phenotype that depends on NLRP3 inflammasome activation." (PMID 39250503, 2024). "The infiltrationof immune cells by macrophages results in the abnomal secretion of adipokines leading to enhanced activation of pyrine domainactivating protein (NLRP3) INFLAMMASOME and increased susceptibility to infection." (PMID 40230956, 2024). "Analyses of cytokines gene expression in the ileum showed that EGS infection promoted increased expression of NLRP3, IL-1β, and TNF in WT-infected when compared with WT-uninfected mice." (PMID 39267751, 2024). "Previous studies have shown that RNA viruses can induce mature IL-1β secretion by activating the NLRP3 inflammasome pathway at different stages of infection." (PMID 39728983, 2024). "NLRP3 inflammasome activation can occur due to various exogenous or endogenous stress factors, such as infection, reactive oxygen species (ROS), damage, metabolites, and adenosine triphosphate (ATP)." (PMID 38172711, 2024).
infection (continued). "When comparing 2-day long infections in the Nlrp3 inflammasome knockout animals, we found that the R20291 ΔcdtB-infected group still lost less weight than those infected with the wildtype strain." (PMID 39298531, 2024). "Following infection, activation of the NLRP3 inflammasome was shown to have either a protective or a detrimental impact on the disease pathology, depending on the infecting Leishmania species (spp)." (PMID 39250503, 2024). "This review also enhances our understanding of the NLRP3 activation mechanism during T. gondii infection, data of value for the development of drugs to improve infection outcomes." (PMID 38623843, 2024). "Probenecid and 25–100 mg/kg baicalin inhibited the mRNA levels of NF-kB, NLRP3 and Caspase-1 compared to those in the infection group (p < 0.05)." (PMID 39075542, 2024). "In the case of macrophage infection by V. vulnificus and V. cholerae, the NLRP3 inflammasome senses the infection, leading to caspase-1 activation and IL-1β secretion." (PMID 39186780, 2024). "NLRP3 inflammasome, mainly expressed in myeloid cells, is activated upon infection by mouse hepatitis virus (MHV), SARS-CoV, MERS-CoV and SARS-CoV-2." (PMID 38932190, 2024). "Inflammasomes, including NLRP3, are a group of multiprotein cytoplasmic receptors that sense pathogen-related and hazard-related molecular patterns in response to pathogen infection and cell injury." (PMID 38355571, 2024). "The NLRP3 inflammasome, a critical regulator of inflammation and infection, has been studied widely." (PMID 37697971, 2024). "In the early stages of IAV infection (the first five days after infection), the activation of NLRP3 triggers the release of inflammatory factors such as IL-1 β and IL-18, which help recruit immune cells and improve their ability to fight the virus." (PMID 38399989, 2024). "Our findings demonstrated that recognition of MDR A. baumannii 1605 infection by the host activates the caspase-1 and caspase-11, resulting in NLRP3/ASC inflammasome activation and the formation of GSDMD pores and induction of programmed cell death." (PMID 39533032, 2024). "Although NLRP3 function is critical for the host defense against infections, dysregulated NLRP3 activity leads to tissue damage." (PMID 39188718, 2024). "Since MRSA UTI is predominantly associated with indwelling urinary catheter use, we modeled CAUTI by placing, via the urethra, a small piece of silicone tubing into the bladder of WT and Nlrp3−/− at the time of infection." (PMID 38392844, 2024). "It appears that NLRP3 has a critical function in regulating infection, hence various research has been undertaken to fully understand its activity." (PMID 38623843, 2024). "Here we provide evidence that NLRP3 directly affects Ym1 expression in myeloid differentiation and polarization after PA infection." (PMID 39405117, 2024). "After PA infection, however, Nlrp3 expression increased in C0, C5, and C6 myeloid cells, without concurrent Chil3 activation, unlike in C2 and C13 cells, where Chil3 was upregulated despite low Nlrp3 levels." (PMID 39405117, 2024). "Conversely, similarly infected NLRP3−/− mice were highly resistant as evidenced for significantly reduced numbers of parasites at 4 and 8 weeks of infection (30 ± 3.6 and 10 ± 3.5 parasites/mouse, respectively)." (PMID 38842647, 2024). "MCC950 was added during the experiment to verify the role of NLRP3 in validating bodies during infection." (PMID 38515339, 2024). "For example, NLRP3 activation is necessary for initiating immune responses required for resolving infections." (PMID 39188718, 2024). "In Nile tilapia, the expression of the NLRP3 gene initially decreased post-infection with Streptococcus agalactiae, and then increased and reached its peak level on the eighth day." (PMID 37834004, 2023). "NLRP3 is the most characteristic inflammasome activated by the infection or stress reaction of cells, which is responsible for the maturation of pro-inflammatory cytokines IL-1β and IL-18." (PMID 36816025, 2023).